EGFR (epidermal growth factor receptor)
Diseases named in the same sentence as EGFR in open-access papers (continued):
Sharing a sentence is not in itself a finding about the gene and the disease.
cancer (continued). "In this study, we designed and synthesized a STING agonist that is conjugated through a cleavable linker to antibodies targeting epidermal growth factor receptor (EGFR), which is overexpressed in a wide range of cancer cells." (PMID 36442099, 2022). "Some of the most frequently activated oncogenes driving diverse cancers are c-MYC, EGFR, HER2, AKT, KRAS, BRAF, and MEK." (PMID 35594991, 2022). "EGFR signaling can also be affected by the Hippo/YAP pathway, which eventually influences cancer progression in HPV + cervical cancer." (PMID 35668455, 2022). "Plitidepsin can induce apoptosis in various human cancer cells by targeting the MAPK and epidermal growth factor receptor signaling pathways." (PMID 36330743, 2022). "EGFR (synonym ErbB1, HER1) plays a crucial role in cancer proliferation, cell mortality, angiogenesis, cell adhesion, and metastasis through multiple downstream pathways (ERK/MAPK, PI3K-AKT, SRC, PLC-γ1-PKC, JNK, JAK-STAT)." (PMID 36428670, 2022). "We have identified that multiple RTKs, such as EGFR, FGFR2, EPHA2, and MET, are key targets for C1GALT1 and their appropriate O-glycosylation is essential for cancer progression and metastasis." (PMID 35169131, 2022). "Tubeimoside V (TBMS-V) activated EGFR and ITGB1-FAK by regulating caveolin-1 (cav-1)-related signal pathway and finally made TNBC cancer cells sensitive to anoikis and inhibited TNBC cell growth and metastasis." (PMID 35414025, 2022). "Their results showed that co-targeting of EGFR and PYK2 and to a lesser extent of EGFR and c-Met yielded the strongest synergistic anti-cancer effect." (PMID 36612135, 2022). "In fact, EGFR was part of a cluster of dysregulated genes and enriched gene sets in the FIR20 cells that define the basal breast (cancer) subtype (LAMC2, TRIM29, COL17A and cytokeratin genes (KRT6, KRT7, KRT13, KRT15))." (PMID 35579852, 2022). "In 2–15% of the cases, the mechanism of resistance to EGFR-TKI in NSCLC involves a histological transformation to small-cell lung cancer (SCLC), highlighting the cancer cell’s plasticity and ability to phenotypically adapt to survive drug pressure." (PMID 35681591, 2022). "Altered expression of AXL in cancer has been studied as a mechanism of acquired resistance to cetuximab and targeting of AXL has been shown to resensitize cells and tumors to EGFR-targeted therapy." (PMID 35461210, 2022). "As a downstream pathway of EGFR, the PI3K/Akt signaling pathway is dysregulated in many cancer cells." (PMID 36387129, 2022). "The epidermal growth factor receptor (EGFR)/AKT/mechanistic target of rapamycin (mTOR) signaling pathway is one of the most important pathways, which is considered as a master regulator for cancer." (PMID 36032960, 2022). "E07 RNA aptamer was generated by protein SELEX for targeting EGFR, which can block EGF binding to EGFR and inhibit EGF-stimulated EGFR phosphorylation and inhibit A431 cancer cell proliferation in 3D cultures." (PMID 36544906, 2022). "The results indicate that berberine can be used as a dual-blocker of both EGFR and HER2 to ensure effective treatment of highly metastatic cancers with EGFR and/or HER2-positive statuses and reduce their drug resistance." (PMID 35269825, 2022). "These drug molecules also showed significant binding performance with some cancer-related PTM-sites (phosphorylation, succinylation, and ubiquitination) of top-ranked four key proteins (EGFR, AURKB, BIRC5, and TOP2A)." (PMID 36567949, 2022). "The epidermal growth factor receptor (EGFR) plays a central role in the development and progression of different cancers." (PMID 35496321, 2022).
cancer (continued). "Customized probes were designed to capture exonic regions of 141 genes selected for the panel, which was aimed for the detection of clinically actionable genetic variations in cancer, including KRAS, NRAS, BRAF, ALK, ROS1, KIT and EGFR." (PMID 35446881, 2022). "In cancer cells, the extracellular domain of NRP1 can interact with EGFR and promote the EGFR signaling cascade elicited upon EGF stimulation." (PMID 35347234, 2022). "MiRNAs exert their function (proliferation, invasion, or epithelial-mesenchymal transition) by targeting specific genes involved in cancer-related signaling pathways, including the Wnt/β-catenin, PI3K/AKT, TGF-β/Smads, and EGFR pathways." (PMID 35465317, 2022). "Over the past two decades, TKIs and monoclonal antibodies targeting EGFR and HER2 were developed and applied for the front- and subsequent-line treatments of human cancers." (PMID 36145516, 2022). "The study was carried out to investigate the prognostic value of Beclin 1, EGFR and ALK for this cancer." (PMID 36401689, 2022). "KRAS mutations lead to abnormal cell proliferation and oncogenic transformation, promote cancer metastasis, and increase the resistance of several cancer types, including CRC, to chemotherapy and epidermal growth factor receptor (EGFR)-targeted therapy." (PMID 36452508, 2022). "Previous studies have shown that CD148 dephosphorylates growth factor receptors and their signaling molecules, including EGFR and ERK1/2, and negatively regulates cancer cell growth." (PMID 34791835, 2022). "Epidermal growth factor receptor (EGFR) and cellular-mesenchymal to epithelial transition factor (c-Met) are widely expressed on cancer cells." (PMID 35899447, 2022). "NF-ƙB, EGFR, PTEN/PI3K/AKT, Wnt, HIF-1α, STAT3 and AKT/ERK/mTOR signaling pathways are among those being influenced by dysregulation of miR-671 in different cancers." (PMID 36545507, 2022). "In EGFR-activated cancer cells, the PI3K/AKT pathway is frequently altered, which aids cancer cell survival and resistance." (PMID 36080307, 2022). "Upon KRAS G12C inhibition, subpopulations of cancer cells that enter a quiescent state can stimulate a compensatory increase in active, GTP-bound KRAS G12C protein via EGFR and aurora kinase signaling." (PMID 34990404, 2022). "Protease-activated receptor 2 (PAR-2), a member of a family of GPCRs, is frequently overexpressed in various human cancers, and that PAR-2-induced cisplatin resistance is dependent on EGFR transactivation in cervical cancer." (PMID 36471329, 2022). "Patients with EGFR mutant aNSCLC progressing on EGFR TKIs and developing an FGFR1/2/3 fusion were selected from the ED of Davidoff Cancer Center (DCC) and Oncology Department, Bnei-Zion hospital (BZ) (April 2014–April 2021)." (PMID 35566609, 2022). "EGFR, followed by RAS activation, induces SUMOylation of Otubain-2 (OTUB2), thereby promoting deubiquitination of YAP/TAZ and stabilizing them in cancer cells." (PMID 36294681, 2022). "In cancer cells, NRP1 mediates ligand-induced EGFR clustering and endocytosis, leading to intracellular activation of the AKT signaling cascade." (PMID 35347234, 2022). "We further illustrate that CHD6-TMEM65 axis is deregulated in cancer and that co-administration of Wnt inhibitor LGK974 and the anti-EGFR monoclonal antibody cetuximab largely restricted the growth of patient-derived xenografts of CRC." (PMID 36473865, 2022). "Both DVD-Ig and KIH formats of anti-EGFR/PD-L1 BsAbs significantly enhanced T cell-mediated cytotoxicity of MDA-MB-231 and BT-20 cancer cells when compared with T cells-only incubation." (PMID 35890277, 2022). "Both LPS- and IL-10-stimulated macrophages induce the phosphorylation of EGFR, Akt, and ERK1/2 in cancer cells." (PMID 35955576, 2022). "The overexpression of EGFR and its ERK1/2 and AKT downstream signalling pathways is common in cancer including CRC." (PMID 35120511, 2022). "However, not all cancers harboring EGFR mutations are sensitive to EGFR-TKIs." (PMID 35626123, 2022).
cancer (continued). "This resistance by the newly synthesized KRAS protein can occur from the activation of the epidermal growth factor receptor (EGFR) and PI3K–AKT–mTOR pathway in cancer cells." (PMID 36614109, 2022). "At the transcriptional level of CC, EGFR, HSP90AA1, and SRC expression levels were significantly different between normal and cancer tissues (all p < 0.05)." (PMID 36569844, 2022). "EGFR, phosphatidylinositol 3-kinase (PI3K)/AKT, and RAS/MAPK signaling are key regulators of metabolism, including lipid metabolism, in cancer." (PMID 35159223, 2022). "K-RAS, epidermal growth factor receptor (EGFR) and anaplastic lymphoma kinase (ALK) can induce PD-L1 expression in cancer cells." (PMID 36499710, 2022). "Several growth factor receptors, including EGFR/HER1, HER2, and FGFR, are known to be overexpressed on the surface of various cancer cells." (PMID 35456655, 2022). "SW620 and CW-2 cells, which expressed EGFR at the highest and lowest levels, respectively, were used to test the targeting potential of EGFR-Lipo-CPT-11 in EGFR-expressing cancer cells." (PMID 35918704, 2022). "Fourteen previously identified anti-inflammatory compounds i.e., 1, 3, 4 oxadiazoles derivatives by our own group were selected for their anti-cancer potential, targeting the tyrosine kinase (TK) domain of VEGFR2 and EGFR." (PMID 36358960, 2022). "Since the EGFR-activating mutations reside near the ATP cleft targeted by EGFR-TKI, we thus assessed whether our probe has altered the effects on EGFR activation and the downstream signaling pathways, including PI3K-AKT-mTOR and RAS-RAF-MEK-ERK in several cancer cells." (PMID 36376325, 2022). "The EGFR was found to regulate DNA damage repair mediated via PI3K/AKT and ERK1/2 pathways in cancer." (PMID 35453686, 2022). "Based on correlations with transcript expression, anti-cancer drugs were clustered, wherein drugs with targets from similar gene classes were more closely clustered, such as HDAC- and EGFR-targeted drugs." (PMID 36357395, 2022). "Several tyrosine kinase inhibitors (TKI) have been approved for cancer treatment including those that target the epidermal growth factor receptor (EGFR, also referred as erbB1, Her1)." (PMID 36009762, 2022). "This is particularly relevant for EGFR signalling, which produces IP3 signals for ER calcium release and regulation of cancer cell growth." (PMID 36497413, 2022). "There were a higher proportion of patients with comorbidities, history of malignant tumor, CVC, mitomycin, recombinant human endostatin, EGFR-TKI, Platinum-based chemotherapy, and Bevacizumab in patients who had VTE compared to patients without VTE." (PMID 35321110, 2022). "There is a high epidermal growth factor receptor (EGRF) expression in certain cancers, and ERL inhibits EGFR." (PMID 35209054, 2022). "Studies have reported that the miR-146 was downregulated in various cancers, including non-small cell lung cancer (NSCLC), and its upregulation inhibits cellular proliferation by directly degrading the EGFR mRNA." (PMID 35511336, 2022). "High expression of EGFR causes enhanced signaling downstream, promoting cell proliferation and inhibiting apoptosis; gefitinib is an EGFR-TKI that binds EGFR reversibly and plays a role in treating various cancers." (PMID 36612173, 2022). "Overexpression or gene amplification of EGFR and HER2 is frequent in multiple cancers, including OC." (PMID 35620395, 2022). "Integrin β3 plays a key role in the resistance to epidermal growth factor receptor tyrosine kinase inhibitors (EGFR-TKI), but the development of integrin β3 inhibitors has been stalled due to the failure of phase III clinical trials for cancer treatment." (PMID 35805163, 2022). "These include EGFR, MAPK, and Src, well-known to coordinate proliferation and progression in several cancers Drug screening of targeted therapies revealed several pan-active compounds that show promise as CCA therapeutics." (PMID 35764936, 2022).
cancer (continued). "EGFR, HER2, ALK, AXL, FLT3, PDGFR and other receptors and signal transducers (e.g., Raf) are involved in the metastasis of various cancers." (PMID 35477123, 2022). "EGFR is also an upstream protein in the PI3K/AKT signal transduction pathway, which is an important target in cancer research." (PMID 35504024, 2022). "Mutations in multiple genes, including epidermal growth factor receptor (EGFR), anaplastic lymphoma kinase (ALK), ROS1, and KRAS, can promote the progression of this cancer." (PMID 36467503, 2022). "CNS metastases occur frequently in patients on EGFR-TKIs, due to the inability of first and second-generation agents to overcome both the BBB and the acquired resistance of cancer cells in the CNS." (PMID 35884398, 2022). "Overexpression of FER has been identified in several cancer types, and FER has been shown to activate MAP kinase signaling by phosphorylating receptor tyrosine kinases including EGFR and MET." (PMID 35706047, 2022). "Oligoprogression is a recently acknowledged pattern of disease progression on systemic anti-cancer therapy raised specifically for oncogene addicted NSCLC, including the EGFR-mutant group." (PMID 35159099, 2022). "Given that EGFR and CD24 are already proposed and in the process of being therapeutically exploited, we now propose VCAM1 as a novel biomarker and target for cancer-specific stratified immunotherapy." (PMID 36221114, 2022). "Quercetin reduces the propagation of cancer cells via the inhibition of intracellular signaling, i.e., PI3K, EGFR, and Her2/neu." (PMID 36247004, 2022). "Overexpression of CD46 protected the cancer cells from both CDC and ADCC, suggesting that the EGFR-targeted anticancer agent cetuximab downregulated the expression of CD46 to maximize the cell-killing activity, thereby affecting both CDC and ADCC." (PMID 36575233, 2022). "Western blot analysis and quantification of EGFR levels confirmed that A431 cells have greater expression of EGFR compared to HeLa, whereas the lowest EGFR levels were observed in the MCF-7 cancer cell line." (PMID 36499115, 2022). "Although former studies reported distinct EGFR-dependent cellular responses to various ligands, the paracrine influence of stromal EREG on global expression profiles of cancer cell subpopulations, more specifically, PCa cells, remain underexplored." (PMID 36202915, 2022). "These pharmacological agents regulate cancer promoting pathways such PI3K/AKT, EGFR and ERK1/2/MAPK to promote apoptosis and repress proliferation, migration, angiogenesis and invasion of cancer cells." (PMID 36033439, 2022). "Other relevant cancer targets, such as translational elongation and initiation factors (e.g., EIF4E), membrane receptors (e.g., EGFR), as well as RNA binding proteins, also showed a tendency towards better recovery, albeit not statistically significant." (PMID 35457260, 2022). "Cetuximab is a monoclonal antibody (~150 kDa) that confers selectivity for epidermal growth factor receptor (EGFR), which is often overexpressed in several types of cancers." (PMID 35336019, 2022). "Flourishing epidermal growth factor receptor (EGFR) is considerably conjoined with stemness, drug resistance and metastasis in various cancers, in particular TNBC." (PMID 35725558, 2022). "As for Cluster Two, the genes were significantly enriched in pathways in cancer, PI3K-Akt signaling pathway, EGFR tyrosine kinase inhibitor resistance." (PMID 35910372, 2022). "Previous studies have shown that Navitoclax synergize effectively with targeted therapies such as EGFR inhibitors in NSCLC and MEK inhibitors in KRAS mutant cancers and BRAF mutant melanoma." (PMID 35256598, 2022). "EGFR is overexpressed in HNSCC and can activate related pathways leading to the proliferation of cancer cells." (PMID 36483049, 2022). "Quantification of EGFR expression shows that A431, HNSCC, HTC-116 cancers have the highest EGFR levels, whereas HeLa or MCF-7 cells possess lower expression." (PMID 36499115, 2022).
cancer (continued). "The epidermal growth factor receptor (EGFR), a receptor tyrosine kinase (RTK), has been reported as an oncogenic signal in various types of cancer." (PMID 35237300, 2022). "Results from the current study suggest that the combination of PTA PPy, Fenton reaction-inducing IO, and the TKI AF, which targets the WT EGFR in combination with NIR, can be a potential cancer treatment." (PMID 36291827, 2022). "The relationship between EGFR signaling and DNA methylation, however, is still somewhat understudied in both HNSCC and other cancer types." (PMID 35224804, 2022). "And EGFR, VEGFR and BRAF targets in MAPK signaling pathway has been extensively studied for promising cancer treatment." (PMID 35439731, 2022). "Small molecules that inhibit EGFR/HER2 can prevent the process of tyrosine kinase phosphorylation and accordingly, suppress the upregulated intracellular signals in cancer cells." (PMID 36678540, 2022). "In this study, for the first time, we identify that the claudin proteins play an important role in EGFR-TKI resistance and determine the effects and mechanisms of this claudin protein in the regulation of gefitinib resistance and cancer stem-like properties." (PMID 35301287, 2022). "PAK regulates cancer cell growth via several signaling pathways, including the WNT/β-catenin, EGFR/HER2/MAPK, and PI3K/AKT pathways." (PMID 35433481, 2022). "In this work, we systematically evaluated proteome remodeling driven by well-known oncogenes (c-Myc, EGFR, HER2, AKT, KRAS, BRAF, or MEK) expressed in isogenic models and relevant cancer-derived and patient-derived pancreatic cancer and osteosarcoma." (PMID 35594991, 2022). "Epidermal growth factor receptor and the EGF family of peptide growth factor play a vital role in the pathogenesis, development, and progression of cancers." (PMID 36144625, 2022). "In order to identify genetic modifiers of therapeutic responses in EGFR-mutant LA, we performed targeted next-generation sequencing (NGS) of 324 cancer-relevant genes in 591 EGFR-mutant LA human tumors (median coverage depth = 500x)." (PMID 35579943, 2022). "EGFR, a receptor tyrosine kinase, upstream of central signalling pathways such as PI3K/AKT and RAS/RAF/MEK/MAPK pathways, is often altered in cancer." (PMID 36012105, 2022). "Betulinic acid and curcumin exerted repressive effects on EGFR levels in 253JB-V and KU7 cancer cells." (PMID 36615262, 2022). "On the other hand, SRC, CASP3, EGFR, ERBB2, mTOR, MMP9, and HIF1A followed the proteoglycans in cancer (degree 7)." (PMID 35959427, 2022). "Numerous important target molecules of AFs in NSCLC and other cancers, such as vascular endothelial growth factor (VEGF) and epidermal growth factor receptor (EGFR), have all become clinical targets for antitumor angiogenesis." (PMID 35664334, 2022). "Other known molecular targets such as epidermal growth factor receptor (EGFR), PARP, and VEGF are known but common for all cancers." (PMID 36158215, 2022). "Epidermal growth factor receptor (EGFR), a prototypical receptor tyrosine kinase, has been extensively investigated as its aberrant expression leads to diseases such as cancer and diabetes." (PMID 35794108, 2022). "Of note, an altered kinase signaling network involving EGFR, PDGFR, PAK1, PTK2 (FAK), PRKCD, and MAP2K2 appear to regulate the aberrant changes in the cancer cells and the TME accompanying recurrence." (PMID 35919862, 2022). "In cancer cell lines, ouabain activates Src kinase and PI3K/Akt/mTOR; Src kinase mediates activation of EGFR and downstream Ras/MAPK signaling." (PMID 35150740, 2022). "A recombinant protein was developed, consisting of an anti-EGFR nanobody fused to the C1C2 domain of lactadherin, which binds to PS present on the surface of EVs, directing these modified EVs to EGFR-positive cancer cells." (PMID 36354586, 2022).